CCL5 (C-C motif chemokine ligand 5)
Diseases named in the same sentence as CCL5 in open-access papers (continued):
Sharing a sentence is not in itself a finding about the gene and the disease.
neurodegenerative disease (16 papers, 2014 to 2025). A disorder of the central nervous system characterized by gradual and progressive loss of neural tissue and neurologic function. "The chemokine CCL5 has been implicated in a wide array of pathological conditions in the brain and in neurodegenerative diseases." (PMID 27400875, 2016). "Elevated CCL5 expression in the central nervous system is associated with increased neuroinflammation, cortical synaptic excitability, and hyperalgesia, and is implicated in neuroinflammatory and neurodegenerative disease." (PMID 37996407, 2023). "Ccl4 and Ccl5 are mainly involved in the infiltration and activation of immune cells, including microglia, and have been implicated in the progression of several neurodegenerative diseases." (PMID 36551859, 2022). "Taking into consideration that decreased amount and activity of PMCA may underlie many neurodegenerative diseases, here we analyzed whether the modified profile of plasma membrane calcium pumps can influence cell response to CCL5-induced signaling." (PMID 31032369, 2019). "Although the exact mechanisms of BEC-induced microglia cluster in neurodegenerative diseases remain mysterious, the chemokine CCL5 released by BECs is confirmed to attract the resident brain microglia during systemic inflammation." (PMID 36908787, 2023). "In the aging brain increased BBB permeability, augmented leukocyte infiltration, and more severe CCL5 action under less efficient neuronal Ca2+ extrusion mechanism could accumulate potentially harmful changes in neurons, which increase the risk of developing neurodegenerative diseases." (PMID 31032369, 2019). "Interleukin-6 (IL-6) and chemokine ligand 5 (CCL5), also known as RANTES (regulated on activation, normal T cell expressed and secreted), have been implicated in neurodegenerative diseases including PD." (PMID 25587378, 2014). "In addition, we believe that it will also be a potentially valuable idea to expand the scope of exploring CCL5/CCR5 axis to other neurodegenerative diseases." (PMID 37769321, 2023). "Whether the chemokine CCL5 leads to the clustered microglia in the perivascular area in neurodegenerative diseases needs to be verified by future research." (PMID 36908787, 2023). "Given that Ccl5 expression is increased in other disorders of neuroinflammation, we measured serum CCL5 levels in other mouse models of lysosomal storage and neurodegenerative diseases." (PMID 31883529, 2019). "We have analyzed chemokines CCL2, CCL5 and IL-8; as well as cytokines TNF-α and IL-1β as they are known to be involved in the pathogenesis of neurodegenerative diseases including PD." (PMID 26275153, 2015). "In degenerative diseases, upregulated CC chemokines MCP-1 (CCL2), MIP-1α (CCL3), and RANTES (CCL5) are possibly involved in the migration of endothelial progenitor cells during tissue repair, with MCP-1 and MIP-1α able to mobilize mesenchymal stem cells into ischemic brain lesions." (PMID 29109449, 2017). "CCL2 and CCL5 play a crucial role in the brain, but their alterations have not been well studied in systemic immunity in neurodegenerative diseases." (PMID 25635231, 2014).
neurological diseases (13 papers, 2012 to 2025). "The CCL5/C-C chemokine receptor 5 (CCR5) axis comprising CCL5 and its main receptor CCR5 is involved in multiple pathologic states such as tumors, infectious diseases, and nervous system diseases." (PMID 37769321, 2023).
metabolic disorders (8 papers, 2016 to 2026). "Surprisingly, deletion of Ccl5 did not rescue the gross metabolic phenotype observed in miR-146a-/- mice subjected to HCC induction, indicating that miR-146a plays an independent role in regulating HCC and metabolic disease." (PMID 41718085, 2026).
adenocarcinoma (7 papers, 2010 to 2025). A common cancer characterized by the presence of malignant glandular cells. "However, the nuclear and membrane expression of CCL5 were found to be similar to poorly differentiated adenocarcinoma cells of CCR5 with less average median value (37, 22, 16 for nuclear expression of CCL5 in poorly, moderately and non-neoplastic cells)." (PMID 29358632, 2018). "Among the adenocarcinoma tissues, the poorly differentiated tissues had high expression of CCR5 and CCL5.We further quantify the expression level in tissue using the Histo Quest software; hematoxylin staining was used as a master marker for cell identification on the basis of nuclear detection." (PMID 29358632, 2018).
hematological malignancies (7 papers, 2014 to 2024). "For example, CCL5, abnormal expression and activity of CCL5/CCR5 axis have been found in hematological malignancies and solid tumors." (PMID 37325644, 2023). "There are no studies on the involvement of CCL5 polymorphisms in the development of hematological malignancies." (PMID 36983384, 2023). "In this context, the C-C chemokine ligand 5/C-C chemokine receptor type 5 (CCL5/CCR5) axis is gaining increasing attention, since abnormal expression and activity of CCL5 and its receptor CCR5 have been found in hematological malignancies and solid tumors." (PMID 32630699, 2020).
infectious disease (7 papers, 2008 to 2023). A disorder directly resulting from the presence and activity of a microbial, viral, or parasitic agent in humans. "Our laboratory and others have also demonstrated that CCL5 deficiencies found in man and animals can increase the susceptibility and progression of infectious diseases by modulating mucosal immunity." (PMID 18700040, 2008). "Other potential targets for CCL5 release reduction include demyelinating and infectious diseases, as studies assessing the CSF from people with MS have revealed increased CCL5 levels among patients with an active form of disease." (PMID 37765263, 2023). "Single nucleotide polymorphisms (SNPs) found in CCL2 and CCL5 gene (chromosome 17), in CCR2 and CCR5 gene (chromosome 3) have been related to infectious diseases including West Nile virus, dengue, HIV24,25, Hepatitis C26 and tuberculosis." (PMID 29057937, 2017).
kidney (4 papers, 2012 to 2023). "Thus, we next analysed whether treatment with [44AANA47]-CCL5 also leads to reduced immune cell infiltration during chronic liver injury with CCl4." (PMID 22574195, 2012).
psychiatric disorder (3 papers, 2018 to 2022). A disorder characterized by behavioral and/or psychological abnormalities, often accompanied by physical symptoms. "However, CCL5 plays a role in controlling neurotransmission by modulating glutamate release at the synapses and dysregulation of CCL5 mediated glutamatergic transmission is linked with psychiatric disorders." (PMID 32218146, 2020).
central nervous system disorder (2 papers, 2015 to 2025). A disease involving the central nervous system. "Related studies have indicated that CCL5 is significant in promoting synaptic growth and memory formation, and it plays a role in central nervous system disorders, particularly those associated with neuroinflammatory processes." (PMID 40004526, 2025).
inflammatory myopathies (2 papers, 2022 to 2025). "Moreover, the expression of CCL4 and CCL5, along with their requisite receptors has been reported in biopsies from patients with inflammatory myopathies." (PMID 36426551, 2022).
benign tumor (1 paper, 2021). "In mouse optic glioma, another NF1 benign tumor, CCL5 is expressed in microglia (the central nervous system equivalent of macrophages)." (PMID 33413690, 2021).
blood cancer (1 paper, 2020). "However, to our knowledge, our results are the first that support the hypothesis that in blood cancer/AML, increased CCL5 release from AML blasts mediates resistance to PKC412." (PMID 31955503, 2020).
colon polyps (1 paper, 2022). "The colon polyps demonstrated decreased expressions in CCL5, CCL18, CCL19, CCL21, CXCL12, CXCL14 and CXCL13 genes in this research." (PMID 35486660, 2022).
connective tissue diseases (1 paper, 2025). "In connective tissue diseases like SLE and RA, CXCL12 facilitates the migration of immune cells to inflammatory sites, while CCL5 amplifies the recruitment of T cells and monocytes, promoting chronic inflammation and tissue damage." (PMID 39860439, 2025).
endocrine system disease (1 paper, 2021). "Besides, the disease susceptibility prediction found that aberrant expressed CCL5 and CCL20 were mainly related to gastrointestinal disease, endocrine system disease, and the disease of cell proliferation disorder (including LIHC)." (PMID 34938730, 2021).
CCL5 also shares sentences with these, for which no sentence is quoted: immune diseases (7 papers); dermatitis (5); medulloblastoma (5); Parkinson’s (5); ulcerative colitis (5); uveal melanoma (5); acute lung injury (4); cystic fibrosis (4); Duchenne muscular dystrophy (4); falciparum malaria (4); heart disease (4); pulmonary TB (4); trigeminal neuralgia (4); age-related macular degeneration (3); autism spectrum disorder (3); bacterial sepsis (3); bronchitis (3); chorioamnionitis (3); chronic gastritis (3); chronic periodontitis (3); colon (3); diabetic retinopathy (3); E. coli infection (3); Glucose intolerance (3); head and neck squamous cell carcinoma (3); hypercholesterolemia (3); idiopathic pulmonary fibrosis (3); juvenile idiopathic arthritis (3); keloid (3); meningococcal disease (3).
A further 263 diseases each share a sentence with CCL5 in 3 papers or fewer.